RNU6-455P (RNA, U6 small nuclear 455, pseudogene)
Gene: Small nuclear RNA gene on chromosome 14 (31,686,692 to 31,686,798, reverse strand). Ensembl gene ENSG00000207412.
Homologues: Orthologues: chimpanzee U6 (99% identical), pig U6 (79% identical). Paralogues in human: RNU6-1060P (90% identical), RNU6-116P (90% identical), RNU6-15P (90% identical), RNU6-949P (90% identical), RNU6-21P (89% identical), RNU6-33P (89% identical), RNU6-47P (89% identical), RNU6-480P (89% identical), RNU6-657P (89% identical), RNU6-672P (89% identical), RNU6-1 (88% identical), RNU6-1152P (88% identical), and 1283 more.